OR5H1 (olfactory receptor family 5 subfamily H member 1)
Description:
Odorant receptor.
Synonyms: HTPCRX14; HSHTPCRX14
Tractability: Antibody: UniProt places it where antibodies can reach, with medium confidence; UniProt predicts a signal peptide or a membrane-spanning region; its Gene Ontology location is reachable by antibodies, with medium confidence.
Gene: Protein-coding gene on chromosome 3 (98,130,721 to 98,138,548, forward strand). Ensembl gene ENSG00000231192.
Subcellular location: Cell membrane
Pathways (Reactome):
Sensory Perception: Expression and translocation of olfactory receptors
Gene Ontology:
Molecular function: protein binding; odorant binding; olfactory receptor activity; G protein-coupled receptor activity
Biological process: sensory perception of smell; detection of chemical stimulus involved in sensory perception of smell; G protein-coupled receptor signaling pathway
Cellular component: plasma membrane; membrane
Genetic constraint (gnomAD): Loss-of-function variants: 0 observed, 0.25 expected, observed/expected ratio (o/e) 0, 90% interval 0 to 1.87. That is too few expected variants to judge how well the gene tolerates losing a copy. Missense variants: 376 observed, 358.96 expected, observed/expected ratio (o/e) 1.05, 90% interval 0.96 to 1.14. Synonymous variants: 124 observed, 130.42 expected, observed/expected ratio (o/e) 0.95, 90% interval 0.82 to 1.1.
Homologues: Orthologues: dog OR5H13 (77% identical), mouse Or5h26 (75% identical), rat Or5h17 (75% identical), dog OR5H16 (75% identical), mouse Or5h17 (74% identical), mouse Or5h19 (74% identical), rat Or5h17c (74% identical), rat Or5h26 (74% identical), dog OR5H12 (74% identical), rat Or5h17b (74% identical), dog OR5H9 (73% identical), mouse Or5h25 (73% identical), and 12 more. Paralogues in human: OR5H15 (95% identical), OR5H14 (87% identical), OR5H6 (81% identical), OR5H2 (79% identical), OR5H8 (66% identical), OR5AC2 (61% identical), OR5K1 (50% identical), OR5K4 (50% identical), OR5K3 (49% identical), OR5K2 (49% identical), OR9G4 (48% identical), OR8U1 (47% identical), and 84 more.